BCL2 (BCL2 apoptosis regulator)
Diseases named in the same sentence as BCL2 in open-access papers (continued):
Sharing a sentence is not in itself a finding about the gene and the disease.
tumor (continued). "Regarding NPC, we have recently shown that mRNA expression status of BCL2 is strongly associated with lymph node involvement and presence of distant metastases in patients, and that it may therefore represent a novel unfavorable and independent tumor biomarker of this malignancy." (PMID 23777485, 2013). "miR-205 has been shown to be epigenetically repressed tumor suppressor in PCa that exerts its tumor-suppressive functions in the human prostate through down-regulation of multiple targets such as BCL2, protein kinase C epsilon and androgen receptor (AR)." (PMID 24167554, 2013). "In that study, AKT-1 was shown to operate via the modulation of Bcl-2 and long-lived DC vaccines were potent enough to suppress tumor growth in the therapeutic setting and significantly increased mice survival." (PMID 23870437, 2013). "Immunohistochemically, these spindle tumor cells showed diffuse Vim and Bcl-2 positive reactivity, but S-100 protein and HMB45 were negative." (PMID 24294990, 2013). "One paper additionally reports that the antiapoptotic factor Bcl-2 is strongly expressed in 90% of tumours with CD34 expression in as much as 78% of cases." (PMID 23634309, 2013). "MiRs -15a and -16-1 are well characterized as chronic lymphocytic leukemia (CLL) tumor suppressors through the targeting of Bcl-2." (PMID 23383180, 2013). "The results were correlated with tumour size, presence of positive sentinel lymph node, tumour proliferation and growth markers (Ki-67, c-erbB2, bcl-2)." (PMID 23346250, 2012). "This protein family has been particularly studied in cancer, which led to the classification of Bcl-2 and Bax as oncogenes and tumor-suppressors, respectively." (PMID 22675634, 2012). "Many of its target genes, such as cyclin D1, c-myc, Bcl-2, survivin and p21cip1 have been shown to control tumor cell survival and proliferation." (PMID 22723956, 2012). "The primary anti-tumor agent during this period is clearly anti-CD-20, but its efficacy appears to be enhanced by the simultaneous introduction of as-bcl-2." (PMID 23272153, 2012). "Or, at least, ER is tightly co-expressed with BCL2 and therefore sufficient to be used in combination with Ki67 in the HR-positive tumours." (PMID 22424533, 2012). "Another mechanism of CRPC is through escape from apoptosis due to the loss of the tumor-suppressive gene PTEN and suppression of the anti-apoptotic gene BCL-2." (PMID 22879989, 2012). "The BCL-2 anti-apoptotic pathway promotes cancer cell survival and can render tumor cells refractive to traditional chemotherapy." (PMID 22880001, 2012). "Bax and Bcl-XL were over-expressed in most tumour samples, while a majority of the tumour samples expressed Bcl-2 at levels equivalent to normal OCSE." (PMID 22852863, 2012). "Significantly more patients with high Bcl-2 expressing tumours (greater than median) were treated with RT in addition to surgery (p = 0.011)." (PMID 22852863, 2012). "By immunohistochemistry, both epithelial and spindle tumor cells were strongly positive for bcl-2 and CD99, and the spindle cells were diffusely expressed vimentin in all five cases." (PMID 22862905, 2012). "Such a tight relationship between Bcl-2 denitrosylation and ubiquitination sheds new light on IL-24-induced Bcl-2 degradation and specific tumor apoptosis." (PMID 22629368, 2012). "More recently, our group has established the inherent ability of Bcl-2 to generate intramitochondrial O2∙− by engaging mitochondrial respiration in tumor cells." (PMID 22593827, 2012). "This is further supported by the observation that mitochondrial respiratory rate and O2∙− levels correlated with Bcl-2 expression levels across different tumor cell lines with various endogeneous Bcl-2 levels." (PMID 22593827, 2012). "Paraffin embedded tumour tissue for 342 case subjects was assembled into tissue microarrays, and the level of expression of BCL2 was established by immunohistochemistry." (PMID 23961365, 2012).
tumor (continued). "USP9X inhibition increases tumor cell sensitivity to various chemotherapeutic agents including Bcl-2/Bcl-xL inhibitors." (PMID 23171055, 2012). "VEGF can promote the survival of tumor cells through the induction of Bcl-2 expression which in turn can induce VEGF expression in certain tumor types." (PMID 22363766, 2012). "We report here that tumor-selective replicating adenovirus ZD55-IL-24 leads to Bcl-2 S-denitrosylation and concomitant ubiquitination, which take part in the 26S proteasome degradation." (PMID 22629368, 2012). "We have also previously shown that bcl-2 mRNA expression was reduced following sub-lethal irradiation of tumor cells." (PMID 22389673, 2012). "Tumour BCL2 protein expression scores were grouped into binary categories for comparison with standard prognostic variables including tumour grade, nodal status, ER, PR, HER2 and CK5/6 status." (PMID 23961365, 2012). "Apparently, many cancers depend on the anti-apoptotic activity of BCL-2 for tumour initiation and maintenance." (PMID 22313995, 2012). "The factor 1 (SATB1/HIF-1α-AR/ER/BCL2) pattern in the HR-positive tumours revealed an inverse relation between the two groups of markers with the opposite factor loadings." (PMID 22424533, 2012). "Immunoblot analysis of tumor lysates of mice also revealed downregulation of Bcl-2, Bcl-XL, cIAP1, and Survivin as well as PCNA in lung tumors after PG treatment." (PMID 23284890, 2012). "If we consider only the pleomorphic adenoma samples, BCL-2 overexpression was even higher, corresponding to 88% of these tumours." (PMID 22313995, 2012). "As observed earlier, there is no apparent long-term (>7 days) benefit to the initial administration of as-bcl-2 alone, but its early time influence delays re-growth of a tumor treated with rituximab." (PMID 23272153, 2012). "A straightforward parametric model of tumor progression simulates the control experiments and the independent effects of as-bcl-2 and anti-CD-20 treatments." (PMID 23272153, 2012). "Promoting Mcl-1 ubiquitination and degradation using USP9X inhibitor sensitizes tumor cells to various chemotherapies including Bcl-2/Bcl-xL inhibitors." (PMID 23171055, 2012). "They further underscore the importance to address each Bcl-2 molecule specifically to ascertain that cell death or drug sensitization is restricted to the tumor." (PMID 22292048, 2012). "In parallel, western blot analysis of the expression of Bcl-2 family proteins in the xenograft tumor lysates revealed that dietary GSPs enhanced the levels of Bax while reducing the levels of Bcl-2 and Bcl-xl." (PMID 22905202, 2012). "In MYC/BCL-XL or MYC/BCL-2 mice tumor cells in spleen and liver expressed the myeloid marker MPO but not the T-cell markers." (PMID 22393362, 2012). "Several human small and non-small lung cancer cell lines and tumor specimens have been shown to overexpress Bcl-2." (PMID 22666341, 2012). "In an attempt to improve H101 anti-tumor efficacy, we previously demonstrated that H101 therapy was potentiated by concomitant use of a Bcl2 siRNA." (PMID 23071601, 2012). "NFkB regulates the expression of numerous antiapoptotic proteins associated with tumor survival (bcl-xl, bcl-2, XIAP, c-FLIP, IAP-1, IAP-2, and survivin), as well as genes associated with tumor progression (cyclin D1, c-myc and COX-2)." (PMID 23145063, 2012). "The synergistic effect of MYC and BCL-XL or BCL-2 overexpression on tumor development observed here is in agreement with previous observations in transgenic Eμ-MYC/BCL-2-induced B lymphoma." (PMID 22393362, 2012). "Given the known role of Slug in inhibitting apoptotisis by regulating the Bcl-2, Bax expression and the transactivation of Puma in some tumours, the Bcl-2, Bax, and PUMA mRNA were assayed by RT-PCR and the proteins were identified by western blot." (PMID 23226515, 2012). "In vitro studies in a variety of different cell types have found that high levels of BCL2 protein expression in tumours can result in striking growth inhibition." (PMID 23961365, 2012).
tumor (continued). "Bcl-2 and Bcl-XL are frequently over-expressed in many cancers and contribute to tumor initiation, progression and resistance to therapy." (PMID 23443079, 2012). "ERK1/2 is an important regulator of apoptosis in tumor cells and Bcl-2/Bax is a downstream component in the ERK1/2 signal transduction pathway." (PMID 22415852, 2012). "In a mouse model of oligodendroglioma, coexpression of PDGF-B and Bcl-2 promoted tumor growth and progression to anaplastic disease." (PMID 22431925, 2012). "We found that treatment with CP-P was effective in down regulating the expression of cyclin D1 and Bcl-2 in tumor tissues." (PMID 23284617, 2012). "A recent study showed that high levels of COX activity and mitochondrial respiration in tumor cells lead to an overexpression of Bcl-2." (PMID 22748147, 2012). "Following immunohistochemistry to detect BCL2 tumour samples on tissue microarrays, the median intensity score was 3 (range 0–3)." (PMID 23961365, 2012). "Tumour BCL2 protein expression status has also been previously strongly associated with PR and ER expression." (PMID 23961365, 2012). "Other studies have reported improved prognosis in OSCC patients whose tumours express low levels of Bcl-2 and high levels of Bax." (PMID 22852863, 2012). "This pattern suggests inverse relation between SATB1 and HIF-1α co-expression and the co-expression of AR, ER, and BCL2 in the subgroup of HR-positive tumours." (PMID 22424533, 2012). "The antiapoptotic Bcl-2 protein targets intracellular organelles such as the endoplasmic reticulum, outer mitochondrial and nuclear membranes, and then modulates tumor cells responses to apoptosis." (PMID 22520038, 2012). "In a multivariate analysis the presence of MMP-1 positivity in tumour cells had an independent prognostic value as did Ki-67 and bcl-2 immunoreactivity." (PMID 21835023, 2011). "Depending on the cell type being investigated, WT1 can either activate Bcl-2 and function as an oncogene or suppress Bcl-2 and function as a tumor suppressor." (PMID 22133358, 2011). "Small BH3 mimetic molecules facilitate the activation of pro-apoptotic Bcl proteins by binding to the hydrophobic groove in Bcl-2 and Bcl-XL thus sensitizing tumour cells for apoptosis." (PMID 21854558, 2011). "Our results identified an interplay between the NT-domain, Bcl2 and caspase 8 that helps augment apoptosis and as a consequence, a tumor's response to therapy." (PMID 22069448, 2011). "Previous studies have indicated a high-level expression of Bcl-2 in many tumor tissues, including HCC." (PMID 22216150, 2011). "Other approaches include nano-encapsulation of Bcl-2 inhibitors to increase bioavailability and tumor targeted combinations with vaso-active peptide receptor engrafted sterically stabilized Bcl-2 inhibitor micelle formulations." (PMID 21760983, 2011). "Other studies demonstrate their capacity to bind to and block the function of antiapoptotic molecules expressed on the surface of tumor cells, like Bcl-2, thus inducing programmed tumor cell death." (PMID 22190971, 2011). "Immunohistochemical approaches to differentiate between these entities included the expression of androgen receptor, CD34, bcl-2, TGF-[beta], CD10, and staining for tumor-associated Merkel cells." (PMID 21152127, 2011). "Anti-apoptotic Bcl-2 homologues (e.g. Bcl-2, Bcl-xL, Mcl-1) control the sensitivity to conventional pro-apoptotic therapy of tumor cells." (PMID 21899728, 2011). "This family has also been shown to be repressed and to suppress (in specific tumour types) a series of oncogenes that include c-Myb, Bmi-1, BCL-2, WNT3A, and Wip1." (PMID 21629246, 2011). "In particular, Bcl-2 is overexpressed by endothelial cells of the newly formed blood vessels nourishing the growing tumor." (PMID 22007303, 2011).
tumor (continued). "Kumar and colleagues found that Bcl-2–induced tumor cell proliferation and tumor cell invasion were significantly mediated by interleukin-8." (PMID 21760983, 2011). "One of these molecules, ABT-737, was developed as an anti-tumour agent, induces apoptosis by selectively inhibiting the anti-apoptotic proteins Bcl-2, Bcl-XL, and Bcl-W." (PMID 21854558, 2011). "After treatment with PEG-liposomal L-oHP, tumour cell predominance of apoptosis in tumor-bearing nude mice was induced, and Bcl-2 mRNA and protein expression were down-regulated, whereas Bax was up-regulated." (PMID 21401960, 2011). "The efficacy of this treatment was due to the higher G3139 uptake in tumor cells which led to a marked down-regulation of bcl-2 protein expression." (PMID 21798045, 2011). "By visual examination, the positivity of TS1, anti-Ki67, and anti-Bcl-2 appeared to increase in the remaining viable cells of the treated tumours." (PMID 22214480, 2011). "Except for bcl-2 expression, the significant prognostic factors included: tumor site, Borrmann type, status of lymph nodes, and pathological stage." (PMID 22216342, 2011). "To examine the potential effects of Bcl-2 signaling on the resistance of SS1P in tumor spheroids, we examined the protein expression of several Bcl-2 signaling molecules in spheroids and monolayers." (PMID 21305058, 2011). "This abnormality promotes tumor cell survival through overexpression of the anti-apoptotic protein Bcl-2." (PMID 22151904, 2011). "The most important finding of this study was the independent prognostic value of MMP-1 as well as Ki-67 and bcl-2 expression in tumour cells." (PMID 21835023, 2011). "Bcl-2 and related family members have been a potential therapeutic target since first being implied in tumor cell survival." (PMID 24212653, 2011). "During treatment with177Lu-DOTA-Tyr3-octreotate, the Bcl-2 staining gradually localised to the tumour cell nuclei, and in regrown tumours, it reappeared in the cytoplasm." (PMID 22214480, 2011). "An increase in the intensity of the TS1, anti-Ki67, and anti-Bcl-2 staining per cell was also observed in tumour cells treated with177Lu-DOTA-Tyr3-octreotate." (PMID 22214480, 2011). "Treatment of tumor cells with maslinic acid also resulted in an increase in the expression of Bid and Bax, repression of Bcl-2, release of cytochrome-c and an increase in the expression of caspases -9, -3, and -7." (PMID 21524306, 2011). "In this study, Bcl-2 expression was located in the tumour cell cytoplasm (ER and/or mitochondria) of untreated tumours." (PMID 22214480, 2011). "In the tumour cells which BCL-2(-)BAD(+) the chemosensitivity to the 4 drugs are higher than the BCL-2(+)BAD(+)and BCL-2(+)BAD(-)ones." (PMID 20691103, 2010). "For both Bcl-2 and β1-integrin, extent of staining is the criterion that has been used previously to define positive staining with a cutoff of 10% of tumour cells for Bcl-2 and 25% for β1-integrin." (PMID 21063403, 2010). "Bcl-2 was predominantly expressed in the cytoplasm of cell lines as well as NSCLC tumor cells and this cytoplasmic pattern is consistent with its localization in the inner mitochondrial membrane." (PMID 20459695, 2010). "Well known is the case of TNFα, produced by tumor and immune cells, which leads to the survival of cancer cells by the upregulation of antiapoptotic proteins, that is, Bcl-2, via the activation of the nuclear factor kappa B (NFκB)." (PMID 20339581, 2010). "Bcl-2 and Bax, the two main members of the Bcl-2 protein family, function as tumor anti-apoptotic and pro-apoptotic factors, respectively." (PMID 21122152, 2010). "The most pertinent model was therefore one that included the main effect for tumour size, grade, nodal status, ER, PR, HER2 and BCL2, in addition to time-dependent effects for all variables except tumour size, HER2 and BCL2 (model 2)." (PMID 20664598, 2010).
tumor (continued). "An increase in the ratio of anti- to proapoptotic Bcl-2 proteins has been detected in various cancers and has been correlated to tumor cell survival and apoptosis resistance." (PMID 20182539, 2010). "The impact of differential BCL2 expression was explored by comparing the HR for women with tumours showing varying levels of BCL2 staining intensity using a simple univariate analysis." (PMID 20664598, 2010). "These two related tumors differed in the origin of drug resistance: the MDR of RLS40 tumor is mdr1a/mdr1b-associated and the MDR of RLS tumor is bcl-2-associated." (PMID 20470373, 2010). "To reverse the MDR phenotype of tumor cells, we applied in our experiments two siRNAs: the bcl-2 siRNA targeted to bcl-2 mRNA and the mdr1b/1a siRNA targeted to mdr1b and mdr1a mRNAs." (PMID 20470373, 2010). "Recently, feasibility of a new approach to apoptosis induction has been demonstrated in a range of tumour cells, namely the specific targeting of anti-apoptotic Bcl-2 proteins." (PMID 20576107, 2010). "In a final multivariate model containing tumour size, grade, nodal status, ER, PR, HER2 and BCL2 status, a time-dependent relationship was confirmed for all variables except tumour size, HER2 and BCL2." (PMID 20664598, 2010). "The drug achieves the purpose of cancer treatment by inhibiting the expression of bcl-2 inside the tumor cells and inducing the tumor cell apoptosis." (PMID 20525250, 2010). "In this study, we applied the mdr1b/1a siRNA targeted to mdr1b and mdr1a mRNAs and bcl-2 siRNA addressed to bcl-2 mRNA aiming to reverse the MDR phenotype of tumor cells and increase their sensitivity to chemotherapeutics." (PMID 20470373, 2010). "Results of Figure-5A depict that tumor insult down-regulated Bcl-2 and up-regulated Bax thereby lowering the Bcl-2:Bax ratio and creating a pro-apoptotic environment in these helper cells." (PMID 19812686, 2009). "Gossypol has been shown to induce apoptosis in a variety of tumor cell lines overexpressing Bcl-XL and/or Bcl-2." (PMID 19852810, 2009). "Patients with presence of BCL2, CCND2, BCL6 and LMO2 mRNA in plasma showed higher expression levels for each gene in tumor tissue, although we only observed a significant association for BCL2 mRNA." (PMID 20016842, 2009). "This would further select tumor cells that have elevated levels of anti-apoptotic BCL-2 proteins and make them resistant to chemotherapy or radiotherapy." (PMID 19768117, 2009). "Tumor-bearing mice, which recieved bcl-2 siRNA treatment, displayed a retardation of liver tumor growth by 66.5%." (PMID 22649602, 2009). "Bcl-2 exhibited a generally weak and focal positivity in three cases (5–10% of tumor cells), while two cases were more strongly positive (20–50% of tumor cells)." (PMID 19594492, 2009). "BCL2 was highly expressed in screen-detected tumours (90 vs 83%, P=0.003) and lower rates of Ki-67 positivity (6 vs 15%, P<0.0001) were identified." (PMID 19773756, 2009). "We chose to evaluate three biomarkers, namely Ki-67 (marker of proliferation), Bcl-2 and Caspase-3 (anti- and pro-apoptotic markers) as data exist showing a close relationship between apoptosis and proliferation in untreated tumours." (PMID 19331661, 2009). "Gossypol induces apoptosis in tumor cells with high Bcl-XL and/or Bcl-2 expression levels, leaving normal cells with low expression levels (e.g. fibroblasts, keratinocytes) relatively unaffected." (PMID 19852810, 2009). "Suppressing bcl-2 expression with gene-targeted oligonucleotides facilitated apoptosis induction in tumor cells and increased cell sensitivity to apoptosis-inducing chemotherapeutic drugs." (PMID 22649602, 2009).